SCN9A (sodium voltage-gated channel alpha subunit 9)
Diseases named in the same sentence as SCN9A in open-access papers (continued):
Sharing a sentence is not in itself a finding about the gene and the disease.
erythromelalgia (continued). "Recently, rare variants of genes other than SCN9a were described in patients with clinically verified erythromelalgia: those genes included SCN10A (Nav1.8), SCN11A (Nav1.9), SCN5A (Nav1.5), SCN7A (Nav2.1), SCN8A (Nav1.6), SCN1B (Nav β1 subunit), SCN3B (Nav β3 subunit), TRPA1, TRPV1, WNK1 and NGFR." (PMID 27598514, 2016). "A study of several members that included several generations of 2 Chinese families with hereditary erythromelalgia revealed that the afflicted individuals had one of 2 missense mutations of the SCN9A gene, which encodes the α-subunit of the NaV1.7 sodium channel." (PMID 24278716, 2012). "The p.I141V mutation in SCN4A and SCN5A, as well as its homologous p.I136V mutation in SCN9A, are interesting examples of mutations that have been linked to inherited hyperexcitability myotonia, exercise-induced polymorphic ventricular arrhythmias and erythromelalgia, respectively." (PMID 25741286, 2015). "Inherited erythromelalgia was initially linked to autosomal dominant gain-of-function mutations in the SCN9A gene, which encodes the Nav1.7 voltage-gated sodium channel (VGSC)." (PMID 37628281, 2023). "Given the phenotype of erythromelalgia seen in the patients, albeit extremely late onset in patient 1, we decided to sequence SCN9A as this was the best candidate gene for the disorder in both patients." (PMID 23292638, 2013). "Inherited erythromelalgia has recently been linked to mutations in the gene SCN9A, which encodes the voltage-gated sodium channel Nav1.7." (PMID 17239250, 2007). "Enhanced pain in painful diabetic neuropathies has been associated with genetic variations in Nav1.7, and the anomalous enhancement of resurgent Nav1.7 currents at high temperatures, caused by SCN9A mutations, underlies the episodic heat‐enhanced pain in inherited erythromelalgia." (PMID 40787071, 2025). "Primary erythromelalgia or inherited erythromelalgia (IEM; OMIN 133020) is an autosomal dominant chronic neurological disorder caused by mutations in human SCN9A gene encoding α subunit of Nav1.7 channel, which is abundantly expressed in trigeminal, sympathetic, and dorsal root ganglion neurons." (PMID 31439884, 2019). "Studies have shown that mutations in SCN9A, which encodes the sodium channel protein Na+ (V) 1.7 subunit, are present in some patients with inherited erythromelalgia, but are rare in noninherited cases of erythromelalgia." (PMID 23766902, 2013). "Erythromelalgia is characterized by the combination of recurrent burning pain, warmth and redness of the extremities, and the mutations in SCN9A shift the voltage-dependence of Nav1.7 activation in a hyperpolarized direction, increase ramp currents and slow deactivation." (PMID 31312012, 2019).
epilepsy (52 papers, 2008 to 2025). "There were 1774 SCN9A variants in ClinVar in total, of which 1546 were labeled as being associated with epilepsy." (PMID 40492992, 2025). "There were submissions of “likely pathogenic” (c.596+1G>T) and “pathogenic” (3780G>A[p.Trp1260Ter]) SCN9A epilepsy variants to ClinVar as recently as January 2024." (PMID 40492992, 2025). "A total of 1540 SCN9A variants were presented on ClinVar as having an association with both epilepsy and hereditary sensory and autonomic neuropathy." (PMID 40492992, 2025). "Thirty missense SCN9A variants were detected in 55 patients with epilepsy referred for genetic testing in the West of Scotland over the 5‐year period." (PMID 40492992, 2025). "Nonetheless, research centers and diagnostic laboratories continue to report SCN9A variants in association with epilepsy in the literature or in variant databases." (PMID 40492992, 2025). "A total of 1540 of the 1546 SCN9A variants in ClinVar labeled as being associated with epilepsy were also reported in association with hereditary sensory and autonomic neuropathy." (PMID 40492992, 2025). "Mutations in SCN9A, another epilepsy-associated gene encoding Nav1.7, also contribute to an increase in seizures and show distinct sensitivity to OXC." (PMID 38091244, 2024). "A Y1958C SCN9A mutation, which maps to the tyrosine of the PPxY-motif and abrogates binding, has further been described to cause epilepsy." (PMID 39009827, 2024). "This shows that SCN9A variant-related epilepsy predominantly consists of heterozygous missense variants." (PMID 38174099, 2023). "The SCN9A gene also plays a role in seizures and epilepsy with some variants linked to Dravet Syndrome (OMIM# 607208) and febrile seizures." (PMID 36630088, 2023). "SCN9A was proven to be both a cause of febrile seizure and variable epilepsy phenotypes and a partner with SCN1A in DS." (PMID 35663268, 2022). "Due to the sparsity of SCN9A mutations in epilepsy, reports classifying it as a true epilepsy gene are inconclusive." (PMID 33841294, 2021). "Further to this, independent GWAS studies that show multiple significant associations between SNPs associated with SCN1A/SCN2A and epilepsy and/or febrile seizures, fail to do so for SCN9A." (PMID 33216760, 2020). "NaV1.1 (SCN1A), NaV1.2 (SCN2A), NaV1.3 (SCN3A), NaV1.6 (SCN8A) and NaV1.7 (SCN9A) are genes whose mutations are related to epilepsy." (PMID 33013363, 2020). "Together with findings in UK Biobank these data refute an association of SCN9A with epilepsy, which has important clinical diagnostic implications." (PMID 33216760, 2020). "The presence of SCN9A on these panels and its currently widely accepted status as an epilepsy disease gene, clearly presents a substantial risk of misdiagnosis to patients." (PMID 33216760, 2020). "Further evidence against an association between SCN9A and monogenic epilepsy is provided by a recent study of 31,058 parent-offspring trios, in which ~25% of probands had epilepsy/history of seizures." (PMID 33216760, 2020). "The data presented here is a good example of this, repudiating the proposed autosomal dominant association of the p.(Asn641Tyr) SCN9A gene variant with seizure disorders." (PMID 33216760, 2020). "Previous publications have described an association between the SCN9A gene and forms of epilepsy, leading to inclusion of the SCN9A gene in diagnostic testing panels." (PMID 33216760, 2020). "Published heterozygous SCN9A variants proposed as a monogenic cause of seizure disorders shown alongside gnomAD allele frequency data." (PMID 33216760, 2020). "Five different genes that encode alpha subunits of sodium ion channels have been reported to have mutations that lead to epilepsy; these include SCN1A, SCN2A, SCN3A, SCN8A, and SCN9A, and epilepsy-inducing mutations have also been reported in SCN1B." (PMID 33102526, 2020). "Actually, SCN9A variant is often mentioned as a genetic modifier in SCN1A mutation-associated epilepsy." (PMID 32062735, 2020).
epilepsy (continued). "This study provides evidence for a role of SCN9A in human epilepsies, both as a cause of FS and as a partner with SCN1A mutations." (PMID 19763161, 2009). "In total, 27 SCN9A missense variants associated with epilepsy have been reported in the literature." (PMID 40492992, 2025). "Our objective was to critically appraise the current evidence linking SCN9A variants to epilepsy." (PMID 40492992, 2025). "There were two “likely pathogenic” SCN9A variants on ClinVar, associated with epilepsy." (PMID 40492992, 2025). "The association between familial hemiplegic migraine-related genes (CACNA1A, ATP1A2, and SCN1A) and both migraine and epilepsy, as well as the impact of polymorphisms in pain-related sodium channels SCN9A and SCN10A on migraine chronification, have been further elucidated." (PMID 41404467, 2025). "Despite having the same SCN9A variant, each individual had a different epilepsy diagnosis." (PMID 40492992, 2025). "Therefore, there is a real possibility of patients with epilepsy being mislabeled with a genetic diagnosis if a pathogenic SCN9A variant is discovered." (PMID 40492992, 2025). "In recent years, several studies have proposed SCN9A as a monogenic cause of epilepsy." (PMID 40492992, 2025). "SCN9A variants reported in the literature to be associated with epilepsy." (PMID 40492992, 2025). "However, in more specific or controversial epilepsy topics, ChatGPT made mistakes (incorrect suggestions for epilepsy surgery or relationship between variants in SCN9A and autosomal dominant epilepsy)." (PMID 39416714, 2024). "The epilepsy of patient 4 showed overlap with both GEFS+ and EMAtS, but she and her family members also had a variant in SCN9A, which might have contributed to the epilepsy phenotype, according to the authors." (PMID 37501353, 2023). "After searching in DrugBank, we retrieved a total of 47 anti-epileptic drugs and 151 targets, of which identified 17 target genes (CACNA1A, CHRNA4,CHRNA7,GABRA1,GABRA2,GABRB2,GABRG2,GRIK1,GRIN1,GRIN2B,KCNQ2,KCNQ3,SCN1A,SCN2A, SCN3A,SCN8A and SCN9A) were overlapped with risk genes of epilepsy." (PMID 36006933, 2022). "The same critical thinking could be applied when hastily attributing an etiological condition to a (likely) pathogenic variant (e.g., the relationship of likely pathogenic variants in SCN9A with epilepsy phenotypes is still under discussion)." (PMID 35250806, 2022). "Some SCN9A variants have been found in epilepsy and autism spectrum disorders." (PMID 33841294, 2021). "In addition to pain-related diseases, mutations of SCN9A were associated with epilepsy in some case reports." (PMID 34947986, 2021). "Together our findings strongly refute an association between SCN9A and epilepsy." (PMID 33216760, 2020). "However, more and more studies have shown that SCN9A mutations in patients are also associated with variable epilepsy phenotypes including febrile seizures (FS), GEFS+, and Dravet syndrome (DS) in recent years." (PMID 32062735, 2020). "The SCN9A variants identified as potentially pathogenic subsequent to p.(Asn641Tyr), include a number ([p.(Gln10Arg), p.(Ser490Asn), p.(Lys655Arg), p.(Ile739Val)]) which are present at population allele frequencies inconsistent with them being causative of a monogenic seizure disorder." (PMID 33216760, 2020). "Also Gabrb2 (Gamma-aminobutyric acid receptor subunit beta-2) and Scn9a (Sodium channel protein type 9 subunit alpha) genes, which are implicated in epilepsy, showed altered expression in the transgenic animals (2−∆∆Ct = 0.87, p = 0.23; 2−∆∆Ct = 1.26, p = 0.136, respectively)." (PMID 31698854, 2019). "Using epilepsy panels and WES, we identified rare variants in several genes, including POLG, SCN1A, SCN9A, KIF1A, and CNTNAP2, which were associated with specific clinical characteristics." (PMID 40565516, 2025). "It is clear that there is still uncertainty within the scientific community regarding the SCN9A–epilepsy gene–disease relationship." (PMID 40492992, 2025).
epilepsy (continued). "Although the Epilepsy Gene Curation Expert Panel previously classified the validity of the SCN9A–epilepsy relationship on ClinGen as “limited,” since September 2021 it refutes this relationship." (PMID 40492992, 2025). "Notably, variants in the SCN1A, SCN8A, and SCN9A genes, which encode sodium channel proteins, were found with high frequency in both groups, suggesting that disturbances in sodium channel function may play a significant role in the pathophysiology of epilepsy." (PMID 40565516, 2025). "Significance: In both the epilepsy panel and WES groups, variants in sodium channel proteins, specifically in the SCN1A, SCN8A, and SCN9A genes, were found to have a high frequency." (PMID 40565516, 2025). "Although this study focused on SCN9A and epilepsy, the lessons learned from our investigation can apply more broadly to other gene–disease relationships, especially when interpreting the significance of novel genetic variants." (PMID 40492992, 2025). "Our study, which included an analysis of SCN9A variants from different sources, provides transparent and novel evidence to invalidate the relationship between SCN9A and epilepsy." (PMID 40492992, 2025). "disputed the link between SCN9A and epilepsy, presenting findings from the UK Biobank, and the Amish community in Wisconsin, USA." (PMID 40492992, 2025). "Identifying specific pathogenic variants in genes such as SCN1A, SCN9A, and QARS1 and the recurrent combination of RANBP2 and RYR3 variants underscores the necessity for ongoing research to elucidate their roles in epilepsy development." (PMID 39509559, 2024). "Identifying potentially pathogenic variants like those found in SCN9A and QARS1, as well as frequently co‐occurring combinations like RYR3 and RANBP2, offers valuable insights into the genetic foundations of epilepsy." (PMID 39509559, 2024). "The mutation is associated with epilepsy and neuropathy, and of note, downregulation of the E3 ligase NEDD4-2 is proposed to dysregulate SCN9A in neuropathic pain." (PMID 39009827, 2024). "Mutations in several NaV-α subunits were associated with epilepsy, including NaV1.1 (SCN1A), NaV1.2 (SCN2A), NaV1.3 (SCN3A), NaV1.6 (SCN8A), and NaV1.7 (SCN9A)." (PMID 39728106, 2024). "The proportion of benign epilepsy in patients with SCN9A, SCN11A, and SCN1B variants was relatively high, and the epilepsy control rate was higher than the rate of other variant types." (PMID 38174099, 2023). "SCN1A/SCN2A/SCN8A variant-related epilepsy was generally manifested at an earlier age, while the SCN3A/SCN9A/SCN1B variant-related subtype showed a later age at onset." (PMID 38174099, 2023). "Nav channel mutations are related to epilepsy, including α subunits, such as Nav1.1 (SCN1A), Nav1.2 (SCN2A), Nav1.3 (SCN3A), Nav1.6 (SCN8A), and Nav1.7 (SCN9A), and the β subunit (SCN1B)." (PMID 38174099, 2023). "SCN1A, SCN2A, SCN3A, SCN8A, SCN9A, SCN11A, and SCN1B sodium channel gene mutations were intimately associated with epilepsy and displayed significant heterogeneity in pathogenesis and clinical symptoms." (PMID 38174099, 2023). "Genes potentially associated with FS-related epilepsy include SCN1A, ADGRV1, SCN1B, SCN9A, GABRG2, GABRD, and CPA6." (PMID 35813073, 2022). "Despite the highly similar electro-clinical phenotypes of the enrolled patients, the results obtained through NGS-based tests revealed possible variants in the SCN1A gene and four other epilepsy-related genes (SCN1B, SCN2A, SCN9A, and SCL2A1)." (PMID 35886038, 2022). "The association of SCN9A with epilepsy and other PE, PEPD, CIP phenotypes resembles the role of CACNA1A in causing discrete phenotypes such as epilepsy, familial hemiplegic migraine, and spinocerebellar ataxia and episodic ataxia." (PMID 32466254, 2020).
epilepsy (continued). "In this paper we present the results of our genetic findings and follow-up studies of SCN9A gene alterations in the Amish community and UK Biobank, alongside a fresh appraisal of previous studies investigating the role of SCN9A in epilepsy." (PMID 33216760, 2020). "For example, the following genes were previously thought to be associated with epilepsy: EFHC1, SCN9A, CLCN2, GABRD, SRPX2 and CACNA1H." (PMID 28558813, 2017). "Our objective was to critically appraise the SCN9A–epilepsy gene–disease relationship." (PMID 40492992, 2025). "We should also highlight that SCN9A is not the first or only candidate gene with a disputed association with epilepsy." (PMID 40492992, 2025). "Although SCN9A is currently listed as a “red” gene on the epilepsy PanelApp due to limited evidence supporting its role as a monogenic epilepsy gene, it may act as a susceptibility factor." (PMID 40565278, 2025). "SCN9A has also been posited as a genetic modifier in SCN1A‐related epilepsy." (PMID 40492992, 2025). "There was one “likely pathogenic” SCN9A variant on HGMD, reported in epilepsy." (PMID 40492992, 2025). "Of the SCN9A variants associated with any disease (epilepsy as well as nonepilepsy phenotypes) and predicted to be likely pathogenic or pathogenic, we looked specifically at those not observed in gnomAD, that is, absent from the general population." (PMID 40492992, 2025). "As such, the inclusion of SCN9A in epilepsy genetic testing panels should be reassessed." (PMID 40492992, 2025). "There are 190 SCN9A variants in HGMD, of which 25 were reported to be associated with epilepsy." (PMID 40492992, 2025). "There are very few extant reports on epilepsy caused by SCN9A mutations, and the pathogenesis of GEFS+ without an SCN1A mutation remains arcane." (PMID 38174099, 2023). "This study found no significant enrichment of de novo variants in SCN9A, with no history of epilepsy reported in the two de novo SCN9A variant carriers where this information was available." (PMID 33216760, 2020). "Our finding reports a novel likely pathogenic SCN9A Y1958C heterozygous mutation in a Chinese family with GEFS+ and provides additional supports that SCN9A variants may be associated with human epilepsies." (PMID 32062735, 2020). "SCN9A-related epilepsies identified in clinical patients through WES and/or NGS." (PMID 33013363, 2020). "Finally, two other genes are considered as “susceptibility” genes to FEB syndrome and epilepsy: GABRD (MIM#137163; GEFS+5) and SCN9A (MIM#603415; FEB3B/GEFS+7)." (PMID 24067191, 2013). "While our findings provide highly suggestive evidence of the role of SCN9A in FS and Dravet syndrome, replication in multiple cohorts, combined with functional studies, is needed to confirm a hyperexcitable role of SCN9A in unrelated epilepsy patients." (PMID 19763161, 2009). "The high minor allele frequency in gnomAD of proposed “epilepsy‐associated” SCN9A variants and the lack of multigenerational segregation analysis of phenotype and genotype do not support any causative role between SCN9A and epilepsy." (PMID 40492992, 2025). "There is no convincing genetic evidence to support SCN9A as a causative epilepsy gene." (PMID 40492992, 2025). "NOVA regulation of NMD splicing also controls the levels of SCN9a, a sodium channel initially thought to act primarily in dorsal root ganglia (neurons that do not express NOVA proteins), but more recently found to be mutated in human epilepsy (causing familial febrile seizures;)." (PMID 23359859, 2013). "We propose that the SCN9A gene should not be included in epilepsy gene panels." (PMID 40492992, 2025). "SCN9A is unlike the epilepsy-related VGSC-α subunit molecules SCN1A, SCN2A, SCN3A and SCN8A each of which is expressed primarily in brain, whereas SCN9A is expressed primarily in peripheral nerves." (PMID 33216760, 2020).